PRG3 (proteoglycan 3, pro eosinophil major basic protein 2)
Description:
Possesses similar cytotoxic and cytostimulatory activities to PRG2/MBP. In vitro, stimulates neutrophil superoxide production and IL8 release, and histamine and leukotriene C4 release from basophils.
Synonyms: MBPH; MBP2
Tractability: Antibody: its Gene Ontology location is reachable by antibodies, with high confidence; UniProt predicts a signal peptide or a membrane-spanning region.
Gene: Protein-coding gene on chromosome 11 (57,376,769 to 57,381,150, reverse strand). Ensembl gene ENSG00000156575.
Subcellular location: Cytoplasmic granule
Pathways (Reactome):
Immune System: Neutrophil degranulation
Gene Ontology:
Molecular function: extracellular matrix structural constituent conferring compression resistance
Biological process: basophil activation; histamine biosynthetic process; leukotriene biosynthetic process; negative regulation of translation; neutrophil activation; positive regulation of interleukin-8 production; superoxide anion generation; immune response
Cellular component: extracellular matrix; extracellular region; specific granule lumen; tertiary granule lumen
Genetic constraint (gnomAD): Loss-of-function variants: 24 observed, 24.27 expected, observed/expected ratio (o/e) 0.99, 90% interval 0.71 to 1.39. The upper end of that interval is the gene's LOEUF score, 1.39, which puts it in group 5 of 6, group 1 being the genes least tolerant of losing a copy. Missense variants: 266 observed, 257.38 expected, observed/expected ratio (o/e) 1.03, 90% interval 0.93 to 1.14. Synonymous variants: 106 observed, 97.35 expected, observed/expected ratio (o/e) 1.09, 90% interval 0.93 to 1.28.
Homologues: Orthologues: chimpanzee PRG3 (98% identical), macaque PRG3 (88% identical), dog PRG3 (63% identical), mouse Prg3 (61% identical), rat Prg3 (60% identical), rabbit PRG3 (57% identical), guinea pig PRG3 (50% identical). Paralogues in human: PRG2 (47% identical).
Diseases named in the same sentence as PRG3 in open-access papers:
PRG3 is named in the same sentence as 16 diseases in open-access papers, as found by Europe PMC text mining. Sharing a sentence is not in itself a finding about the gene and the disease. The quoted sentences say what the papers report.
acute myeloid leukemia (1 paper, 2022). Acute myeloid leukemia (AML) is a group of neoplasms arising from precursor cells committed to the myeloid cell-line differentiation. "PRG3 encodes a proteoglykane that has been reported as major regulator associated with survival of acute myeloid leukemia patients." (PMID 35008420, 2022). "Further, an in-depth literature analysis revealed that several of these genes play important roles in cancer (CDCA3, ECEL1, EN1, HLA-DMB, SPRR2A, TMEM40) including acute myeloid leukemia (CDCA3, HLA-DMB, RPL18A, PF4, PRG3) and T cell acute lymphoblastic leukemia (TLX3)." (PMID 35008420, 2022).
brain tumors (1 paper, 2016). "We have identified perturbed PRG3 levels in human malignant brain tumors displaying either elevated or down-regulated PRG3 levels compared to non-transformed specimens." (PMID 27058420, 2016).
coronary atherosclerosis (1 paper, 2022). Atherosclerosis of the coronary vasculature. "In addition to MFGE8, we identified three additional previously unreported loci to be associated with coronary atherosclerosis, TMEM200A, PRG3 and FHL1 being the nearest genes of the lead variants." (PMID 35978133, 2022).
glioblastoma multiforme (1 paper, 2016). "We next analyzed the levels of PRG3 in human glioblastoma samples." (PMID 27058420, 2016). "Moreover, expression analysis revealed opposing PRG3 levels in human malignant gliomas (glioblastoma multiforme, GBM) with specimens showing high levels as well as reduced PRG3 levels." (PMID 27058420, 2016).
glioma (1 paper, 2016). A benign or malignant brain and spinal cord tumor that arises from glial cells (astrocytes, oligodendrocytes, ependymal cells). "Here, we report on the neuronal-associated growth promoting gene PRG3 executing oncogenic cooperation in gliomas." (PMID 27058420, 2016). "Moreover, imbalanced PRG3 expression caused increased colony formation and growth in comparison to wild-type glioma cells." (PMID 27058420, 2016). "Thus, distinctly altered PRG3 levels are associated with malignant gliomas in humans, and challenge glioma cell shape." (PMID 27058420, 2016). "Further studies will relate to the molecular signature of PRG3-derived tumors, i.e. whether various perturbations of PRG3 levels cause different subtypes of gliomas, i.e. such as the development of mesenchymal or neural glioblastoma subtypes." (PMID 27058420, 2016). "In PRG3 and PRG3kd glioma implanted brains, the tumor border displayed a diffuse margin with an invasive pattern." (PMID 27058420, 2016). "These experiments revealed that gliomas with elevated PRG3 levels were significantly more sensitive to Ras inhibition compared to parental tumor cells and PRG3kd gliomas." (PMID 27058420, 2016). "Gliomas with imbalanced PRG3 expression showed stronger infiltrative tumor expansion into brain parenchyma with a polarized and irregular tumor front compared to wild-type gliomas." (PMID 27058420, 2016). "PRG3 overexpression as well as RNAi mediated PRG3 knock down altered F98 glioma cell morphology with elongated and fusiform cell shapes in contrast to control glioma cells giving a more polygonal morphology." (PMID 27058420, 2016). "T2-weighted images further demonstrate augmented perifocal brain edema in PRG3 overexpressing and silenced gliomas compared to wild-type gliomas." (PMID 27058420, 2016). "We determined the expression of C6 and F98 glioma cells with disturbed PRG3 levels by quantitative RT-PCR analysis." (PMID 27058420, 2016). "Deletion of the C-terminal domain in PRG3 (PRG3ΔCT) led to decreased Ras activation compared to control gliomas." (PMID 27058420, 2016). "In this study, we investigated the impact of distinct expression thresholds of PRG3 on glioma morphology and function." (PMID 27058420, 2016). "We next performed histological analysis on brain sections from WT, PRG3 and PRG3kd glioma implanted animals." (PMID 27058420, 2016). "In vivo tumor monitoring by contrast-enhanced T1-weighted 3 Tesla magnetic resonance imaging (MRi) 10 days after implantation further revealed increased tumor volume in PRG3 imbalanced gliomas." (PMID 27058420, 2016). "Further, imbalanced PRG3 levels in gliomas foster Ras-driven oncogenic amplification with increased proliferation and cell migration although angiogenesis was unaffected." (PMID 27058420, 2016). "Comparisons of PRG3 overexpressing, knockdown, and wild-type gliomas revealed that down-regulated PRG3 expressing gliomas grow significantly faster than wild-type and PRG3 overexpressing glioma cells." (PMID 27058420, 2016). "Animals bearing gliomas with imbalanced PRG3 expression showed reduced overall survival compared to wild-type glioma bearing animals." (PMID 27058420, 2016). "We further analyzed PRG3 expression in rodent and murine primary astrocytes and neurons in comparison to glioma cells." (PMID 27058420, 2016). "Initially, we monitored glioma migration and found that PRG3 overexpressing as well as PRG3-silenced gliomas showed accelerated migration." (PMID 27058420, 2016). "In vivo disequilibrated PRG3 gliomas show aggravated proliferation, invasion, and deteriorate clinical outcome." (PMID 27058420, 2016). "Expression of PRG3CT in gliomas amplified proliferation and transformed cellular morphology comparable to PRG3 full length expressing gliomas." (PMID 27058420, 2016). "First, well established murine, rodent and human glioma cells were utilized and deregulated PRG3 expression was induced." (PMID 27058420, 2016).
glioma (continued). "These in vitro assays indicate that perturbed PRG3 expression in gliomas foster oncogenesis and increase their malignancy potential." (PMID 27058420, 2016). "Statistical analysis revealed that both PRG3 overexpressing and PRG3 silenced gliomas showed an accelerated onset and progression of neurological deficits compared to control tumors." (PMID 27058420, 2016). "Deregulated PRG3 expression reduced apoptosis, enhances proliferation, migration and thus elevated the malignancy of glioma cells." (PMID 27058420, 2016). "Transcriptional analysis revealed a more than 50% reduction in PRG3 knockdown gliomas and a 150 fold PRG3 mRNA increase in PRG3 overexpressing gliomas." (PMID 27058420, 2016). "To determine how tumor growth is regulated in PRG3 disequilibrated gliomas we analyzed possible intracellular interaction partners using the C-terminal tail as bait." (PMID 27058420, 2016). "Our results demonstrate that perturbed levels of the primarily neuronal integral membrane protein PRG3 can promote oncogenesis in glioma cells." (PMID 27058420, 2016). "Further, cell growth was monitored in time-lapse mode and revealed that PRG3 overexpressing gliomas grow faster than mock vector transfected gliomas (named as wild type, WT)." (PMID 27058420, 2016). "Notably, PRG3 expressing gliomas were highly sensitive towards Ras inhibition in comparison to PRG3kd gliomas." (PMID 27058420, 2016). "Interestingly, PRG3 overexpressing and PRG3 silenced gliomas conversely increased oncogenic Ras activation compared to wild-type gliomas." (PMID 27058420, 2016). "In addition, deranged PRG3 in gliomas formed also bigger colonies compared to controls, thereby increasing the capability for anchor-independent growth." (PMID 27058420, 2016). "We continued to test whether PRG3-driven malignancy promotes glioma growth also in the context of a complex brain microenvironment including all cellular constituents." (PMID 27058420, 2016). "Hence, gliomas with a neuronal expression signature exhibits strong malignancy which indicates that neural genes such as PRG3 operate in tumor progression and amplified oncogenic signaling." (PMID 27058420, 2016). "In this study we investigated the impact of the PRG3 on glioma morphology and function." (PMID 27058420, 2016). "To test whether imbalanced PRG3 levels are advantageous and long-lasting we analyzed glioma growth in vivo by orthotopic implantation of syngeneic glioma cells into rat brains." (PMID 27058420, 2016). "Thus, gliomas with high PRG3 levels are prone to Ras blockers and their tumor growth can be treated with Ras-inhibiting drugs such as salirasib." (PMID 27058420, 2016). "We next tested whether perturbed PRG3 thresholds as found in human GBMs have an impact on glioma growth and apoptosis." (PMID 27058420, 2016). "Thus, interference with the regulation and homeostasis of PRG3 amplifies malignancy in glioma cells." (PMID 27058420, 2016). "Interestingly, PRG3 overexpressing and PRG3 silenced gliomas showed comparable vascular density to wild-type gliomas." (PMID 27058420, 2016). "Thereafter, we analyzed the cellular effects of various PRG3 levels in glioma cells." (PMID 27058420, 2016). "Thus, our data show that the interference with PRG3 homeostasis amplifies oncogenic properties and foster the malignancy potential in gliomas." (PMID 27058420, 2016). "We then investigated whether an imbalanced PRG3 expression in gliomas affect cell cycle and cell death." (PMID 27058420, 2016). "It is conceivable that oncogenic cooperation in single tumor cells could be one mechanism by which imbalanced PRG3 executes aggravated malignancy in gliomas." (PMID 27058420, 2016). "Interestingly, glioma cells with up and down regulated PRG3 both showed reduced apoptosis compared to wild-type gliomas." (PMID 27058420, 2016). "Interestingly, murine and rodent astrocytes displayed higher PRG3 mRNA expression levels compared to neurons or F98 glioma cells." (PMID 27058420, 2016).
glioma (continued). "Although these data are consistent with the hypothesis that imbalanced PRG3 expression in gliomas amplifies their malignancy, it is conceivable that this tumor growth may not sustainable in vivo due to its altered angiogenesis." (PMID 27058420, 2016). "Moreover PRG3 silencing makes gliomas resistant to Ras inhibition." (PMID 27058420, 2016). "Cell cycle profiling discerned that high PRG3 expression did not significantly alter cell cycle progression compared with wild type glioma cells." (PMID 27058420, 2016).
leukemia (1 paper, 2022). A malignant (clonal) hematologic disorder, involving hematopoietic stem cells and characterized by the presence of primitive or atypical myeloid or lymphoid cells in the bone marrow and the blood. "Importantly, some of these genes have already been reported in relation to CML (e.g., AURKB, AZU1, HLA-B, HLA-DMB, PF4) and others have been found to play important roles in different leukemias (e.g., CDCA3, RPL18A, PRG3, TLX3)." (PMID 35008420, 2022).
malignant glioma (1 paper, 2016). A grade III or grade IV glioma arising from the central nervous system. "Although the PRG-family is a neuron-associated gene family, PRG3 appears to take up a distinct role with regard to choice of cell populations-it is not restricted to central nervous system tissue but identifiable in other organs-as well as in malignant gliomas." (PMID 27058420, 2016). "Analysis of the human expression databases does at least show that a deregulated expression dosage of PRG3 leads to a worse outcome in patients with malignant gliomas." (PMID 27058420, 2016). "The clinical relevance to our findings is further supported by clinical data base studies on malignant gliomas, where PRG3 is expressed in opposing amounts in the way that either PRG3 is elevated in human samples or repressed compared to non-transformed human specimens." (PMID 27058420, 2016). "Experimental data support the human expression traits of PRG3 in malignant gliomas." (PMID 27058420, 2016). "Since even fully differentiated neurons and astrocytes can give rise to full-blown malignant gliomas, genetic lesions affecting PRG3 levels directly or via transcriptional regulation may contribute to oncogenic cooperation in the process of aggravated malignancy." (PMID 27058420, 2016). "In malignant gliomas PRG3 is expressed in opposing amounts in the way that PRG3 is either elevated or down-regulated compared to non-transformed human specimens." (PMID 27058420, 2016).
prostate carcinoma (1 paper, 2005). A carcinoma that arises from epithelial cells of the prostate gland. "PRG-3 appeared to be expressed at high levels in all samples except primary prostate cancer where the expression level appeared low." (PMID 16042785, 2005).
tumor (3 papers, 2005 to 2022). "Proliferation associated protein PRG3 and anti-apoptosis related protein SERPINB9 in Ca vs Liver group, and cyclin-dependent kinases CDKS up-regulated in both primary tumor and liver metastasis tissues." (PMID 36249004, 2022). "This is further evidenced by responses to Ras inhibition in PRG3 expressing tumor cells." (PMID 27058420, 2016). "Its expression pattern suggests that PRG-3 may be expressed in basal cells in normal glands as these cells are missing in tumor glands." (PMID 16042785, 2005). "Moreover, the tumor margins in wild type tumors were less diffuse compared to PRG3 tumors." (PMID 27058420, 2016). "Moreover, diminished PRG3 levels led also to Ras activation although these tumor cells are not prone for Ras inhibition." (PMID 27058420, 2016).
infection (2 papers, 2017 to 2025). The state of being infected such as from the introduction of a foreign agent such as serum, vaccine, antigenic substance or organism. "Our study identified upregulation of both PRG3 and CCR3 in FUN, while in PYL PRG3 was upregulated only at 3–5 dpi, suggesting a differential and physiological role of FUN and PYL during the infection." (PMID 40076885, 2025).
PRG3 also shares sentences with these, for which no sentence is quoted: angina pectoris (1 paper); cancer (1); cardiomyopathy (1); coronary heart disease (1); enteritis (1); Parkinson disease (1).